CD44 (CD44 molecule (IN blood group))
Diseases named in the same sentence as CD44 in open-access papers (continued):
Sharing a sentence is not in itself a finding about the gene and the disease.
tumor (continued). "HA, which is a high-molecular-weight glycosaminoglycan and a major component of extracellular matrix, promotes tumor proliferation, invasion, and migration by binding to the CD44 HA receptor." (PMID 25304388, 2014). "Future studies investigating CD44 expression in large cohorts of human tumor tissue samples will further contribute to the delineation of its role in OS." (PMID 23565227, 2013). "The EMT transcription factors ZEB1/2 have shown to be overexpressed in CSC-like cells in HNSCC and are linked to decreased survival rates, increased sphere formation, CD44+ cells, tumour growth, and metastasis." (PMID 23533441, 2013). "In contrast, only 3 of the 6 mice injected with the 5 × 104 shZEB1 CD44+ CD117+CSCs developed tumor on Day 22, Day 26 and Day 28, respectively; the other 3 mice did not grow tumors throughout the 56-day observation period." (PMID 23842108, 2013). "The CD44+/CD24−/EpCAM+ population sorted from these lines has stem-like properties and is able to initiate tumour formation much more readily than the luminal population (CD44+/CD24+/EpCam+)." (PMID 23436775, 2013). "Our MRI results were confirmed on the molecular level, as we found similar results, such as a 2.3-fold amplification in gene expression of CD44—the surrogate marker for tumor burden in our studies." (PMID 23385555, 2013). "CD44 is highly expressed in many malignancies and is correlated with the tumor biological behavior including tumorigenesis, growth, metastasis and prognosis." (PMID 23445749, 2013). "The populations of ALDHBr and CD44+/CD24− cells exhibited partial overlapping, and the ALDHBr/CD44+/CD24− population showed higher tumor-initiating ability than that of the ALDHBr population or CD44+/CD24− population." (PMID 23967051, 2013). "Although the role of GCSCs in tumor angiogenesis remains obscure, in other solid tumors, such as ovarian cancer, purified CD44 positive cells (also known as ovarian CSCs) have been demonstrated to possess a similar endothelial potential." (PMID 23710217, 2013). "A multivariate including HPV status, CD44 intensity staining, age, sex, stage, and tumor site was performed, but here p16INK4a was excluded due to the high correlation between HPVDNA and p16INK4a overexpression." (PMID 24156023, 2013). "The results show that more brown cells were found in miR-200c-CD44+CD117+CSCs of tumor tissue than the control cells." (PMID 23842108, 2013). "In agreement with in vitro findings, our mouse model data showed that suppression of CD44 in HNSCC cells significantly reduced tumor incidence in vivo." (PMID 24403253, 2013). "Of the 40 neoplasms with the CD44+/CD24- phenotype described in our study, 37 exhibited histological grades II or III, or were of lymph node metastases." (PMID 24119896, 2013). "AT13387 effectively reduced both the number and size of C666-1 tumor spheres with decreased expression of NPC CSC-like markers CD44 and SOX2." (PMID 24156782, 2013). "All these findings provide clues that CD44 plays a role in the regulation of ROS defense and tumor progression." (PMID 23803658, 2013). "As almost all tumor cells are immunoreactive to CD44, we chose this marker as a suitable surrogate parameter to track tumor cells microscopically and to investigate tumor burden on the molecular level (transcripts)." (PMID 23385555, 2013). "The cancer stem cell criteria that we chose were CD44 positivity, tumor sphere formation and boyden chamber invasion." (PMID 24386318, 2013). "In the SW-620 tumor line, the CD44 subpopulation was increased following treatment with SC-1 (n = 3, paired Student’s t test, p = 0.03, mean±s.e.m., control treated: 39.6±8.5% positive, SC-1 treated: 74.1±13.4% positive)." (PMID 23437320, 2013). "They make up a subset of the entire tumor ranging from 10%-60% and can be enriched through flow cytometry sorting for cells with CD44+/CD24−/ESA+/CD49f+ surface marker phenotype and also through non-adherent mammosphere culture conditions." (PMID 23593654, 2013).
tumor (continued). "Previously, some studies using CD44 as a CSC marker have concentrated only on the CD44high population whereas others have isolated the entire CD44-positive population from tumours." (PMID 23437366, 2013). "The reduced tumour initiating ability of CD44+CD24neg DT-22 was reproducibly evident at several different cell numbers injected." (PMID 23982961, 2013). "As has been noted previously, we also witnessed a large variation in the percentage of CD44-positive cells between tumours." (PMID 23437366, 2013). "In the peripheral blood of patients with HNSCC, a greater number of CD44+ tumor cells were also observed compared with that of the healthy control group." (PMID 24179490, 2013). "We also identified that the changes in CD44 positivity in sphere-derived cells are in accordance with ROS levels, indicating the involvement of CD44 in the modulation of ROS status during the EMT in tumor cells." (PMID 23803658, 2013). "Compared with the mice of the two control groups, a few tumor metastasis were found in the lungs of the nude mice injected with the shZEB1 CD44+CD117+CSCs." (PMID 23842108, 2013). "Having shown a greater frequency of sphere and tumour forming cells in CD44+CD24low+ than CD44+CD24neg populations, and a potential precursor–progeny relationship between the two, we next assayed metastatic potential." (PMID 23982961, 2013). "Sun and Wang found that 1000 c-Met+ cells demonstrated self-renewal and were able to generate heterogeneous tumours in 54.4% of cases and that 1000 c-Met+ cells were more tumourigenic than 1000 CD44+, which were only able to generate tumours in 33.3% of cases." (PMID 23533441, 2013). "CD44, a cell-surface adhesion molecule and receptor for hyaluronan, plays an important role in cell migration and tumor growth and progression." (PMID 23372684, 2013). "The CD44+ GC stem-like cells that recorded a positive score in the migration and invasion assay in vitro formed invasive tumours in vivo." (PMID 23833643, 2013). "The CD133+/CD44+ phenotype of PC-3 cells represented a small subpopulation of cells (∼0.53%) within the whole population of tumor cells." (PMID 23426586, 2013). "CD44 is a surface adhesion molecule that binds to hyaluronic acid, which is related with tumor progression and metastasis." (PMID 23902592, 2013). "Expression of CD44, a cell adhesion glycoprotein participating in epithelial cell–stroma interactions and important for tumor invasion and metastasis 8, has previously been described as a prognostic marker in many cancers 9–10." (PMID 24156023, 2013). "Most recently, the frequency of CD44+ cells correlated with poor prognosis, more aggressive tumours, and higher rates of recurrence following radiotherapy." (PMID 23533441, 2013). "The CD44 reactivity on tumor samples was significantly correlated with the absence or presence of metastasis: among cases with no metastases, 90.9% expressed CD44 against only 9.1% of cases CD44-negative (P = 0.013)." (PMID 23445749, 2013). "Further experimentation revealed that the CD44+ stem-like cells that recorded positive scores in the migration and invasion assay in vitro formed invasive tumours in vivo." (PMID 23833643, 2013).
tumor (continued). "To permit comparison between different tumours we identified a stable CD44 variable exon (CD44v) expression pattern, or CD44 ‘fingerprint’." (PMID 23342032, 2013). "The apparent discrepancy between in vitro and in vivo outcomes of CD44 knock-down on tumorigenic and metastatic properties of 143-B cells highlights the essential impact of the tumor environment on OS progression." (PMID 23565227, 2013). "CD44 has been recognized as a contributor to tumor chemoresistance and as a cancer cell and cancer stem cell biomarker due to its overexpression in cancer compared to normal cells (haematopoietic, epithelial, and neuronal cells)." (PMID 24251041, 2013). "We therefore initially isolated NCAM+PSA-NCAM+ or NCAM+CD44+ cell fractions from p-WT Xn by sorting and analysed their tumour initiating capabilities in mice as well as additional stemness characteristics." (PMID 23239665, 2013). "The membrane-bound glycoprotein, CD44, is found expressed in many tumour cell types and is an important factor in tumour growth, invasion and metastasis." (PMID 23349823, 2013). "The number of CD44+ cells in the tumor corresponds with the stage of the disease, as the percentage of positive cells in histological samples rises from 6.3% in primary tumors to 18% in metastatic tissue in representative patients." (PMID 23528888, 2013). "From these results, we suggest that predicting the role of CD44 variable exon expression in tumour progression is more complex than previously anticipated." (PMID 23342032, 2013). "CD44 was also primarily localized to the cell membrane, but was also observed in the cytoplasm and in the interstitial spaces outside of tumor cells." (PMID 23468946, 2013). "Of interest was the fact that due to stimulation by TNFα + Estrogen + EGF, over 50% of the tumor cells acquired high expression levels of both β1 and CD44 together." (PMID 24369447, 2013). "In the MDA-MB-231, as few as 100 CD44+CD24low+ cells yielded orthotopic tumours that generated multi-organ metastasis and lung micrometastasis, while tumours from up to a half million CD44+CD24neg cells failed to metastasize." (PMID 23982961, 2013). "Aberrant CD44 expression is advantageous for the growth, survival, and dissemination of tumour cells." (PMID 24009708, 2013). "They found that as few as 5,000 CD44+ HNSCC cells gave rise to a new tumor when transplanted into the flank of immunocompromised mice, whereas CD44- cells failed to form tumors in the mice." (PMID 24423398, 2013). "Membrane receptors known to interact with CD44 and their downstream signals activate Stat3 leading to tumor progression and invasion." (PMID 23401782, 2013). "IFN-γ also induced downregulation of CD24 expression such that CD44+CD24- stem-like MMC tumor cells were increased from an average 10% to 55%." (PMID 24324806, 2013). "CD44 is the major HA receptor, and interaction with HA is involved in tumor cell adhesion and migration." (PMID 23468946, 2013). "CD44 is thought to be involved in tumour progression and metastasis through its role as a regulator of growth, survival, differentiation, and migration." (PMID 23533441, 2013). "In general, an injection of 1×104 CD44+ cells gave rise to tumours with 80% incidence, with relatively short latency periods (<1 week) in all mice." (PMID 23833643, 2013). "Cultured cells uniformly express CD44 in all three tumor samples, but the labeling intensity is highly variable both between and within the same sample." (PMID 24019906, 2013). "Relapsed ANV tumor cells showed characteristics of stem-like cells which included CD44+CD24- phenotype, Sca1 expression, and high rates of tumorigenicity in vivo." (PMID 24324806, 2013). "The extreme high level of CD44 VE expression in the circulating tumour cells of the newborn animals seems to indicate, that their role is mainly in getting into and/or surviving in the circulation." (PMID 23342032, 2013).
tumor (continued). "Other study has found similar, but not identical, results since the authors compared neoplastic cells in lymph nodes metastases with their corresponding primary tumor and found that metastatic cells contained a higher frequency of CD44+/CD24- cells." (PMID 24119896, 2013). "We have demonstrated that FKBPL and AD-01 bind to the CD44 receptor and inhibit tumour cell migration in a CD44 dependant manner; CD44 knockdown abrogated AD-01 binding as well as its anti-migratory activity." (PMID 23457460, 2013). "Highly reduced expression of CD44 was observed in 1 μM AT13387-treated tumor sphere and loss of both CD44 and SOX2 were observed in 10 μM AT13387-treated tumor sphere." (PMID 24156782, 2013). "On the other hand, primary tumours with high base CD44 VE expression also contain metastatic clones, that either have sufficient CD44 expression or ‘utilize’ other molecules to facilitate metastasis formation." (PMID 23342032, 2013). "Our earlier studies convincingly showed that almost all the MPE primary tumor cells labeled for surface CD44 (>98%)." (PMID 24019906, 2013). "Upon binding to CD44 isoforms, HA initiates tumor cell activities including tumor cell adhesion, growth, survival, migration, invasion, and tumour progression through the activation of intracellular signaling pathways." (PMID 24083250, 2013). "Girdin and PI3K proteins were more highly expressed in CD44+/CD24− tumor stem cells compared to the control group and Girdin and PI3K proteins were co-immunoprecipitated in the MD-231 cell line." (PMID 23760650, 2013). "We show that the significant role of CD44-moesin interaction in cellular migration is in response to hyaluronan, an important component of the tumor microenvironment." (PMID 23855374, 2013). "CD44+CD24low+ are enriched for embryonic stem cell (ES) and metastatic gene expression signatures, tumour sphere, soft agar colony forming and tumour forming cells compared to CD44+CD24neg, and in the MDA-MB-231 model show greater metastatic potential." (PMID 23982961, 2013). "Our group previously characterized tumor-initiating spheroids expressing the surface markers CD44 and CD117 (c-Kit)." (PMID 24280306, 2013). "We therefore investigated how the method of cell isolation from intact tumours, or release from culture, can influence their surface retention of different CD44 isoforms and, consequently, the properties of the cell fraction detected as CD44high CSCs." (PMID 23437366, 2013). "The hyaluronic acid receptor CD44 is found at low levels on the surface of epithelial, haematopoietic, and neuronal cells and is overexpressed in many cancer cells particularly in tumour initiating cells." (PMID 23533773, 2013). "Because the cells located in the periphery and center of the tumor responded differently to docetaxel, CD44 and CD24 expression was analyzed in both regions." (PMID 23301003, 2013). "WT MMC and relapsed MMC tumor cells were then analyzed for the expression of neu and the stem cell markers CD44 and CD24." (PMID 24324806, 2013). "The tumor cells remained highly positive for the CD44 marker, with 98.2% of cells staining positive, although the CD44-MFI was even higher than the originally implanted cells." (PMID 24019906, 2013). "Both CD44 and SOX2 CSC-like markers were overexpressed in the C666-1 tumor sphere and the isolated CD44+ NPC cells were found to be more resistant to chemotherapeutic agent." (PMID 24156782, 2013). "The in vivo tumor formation assay revealed that CD44+/CD24- cells had the highest tumorigenic capacity compared to the other three subsets." (PMID 23799994, 2013).
tumor (continued). "The ability of CD44+CD24low+ to generate both cell types, while CD44+CD24neg cells generated only like progeny was also observed in two independent primary dissociated tumour cultures, DT-22 and DT-25." (PMID 23982961, 2013). "The CD44-targeted liposomes were found effective in reducing tumor size, highlighting their potential to be used for selective chemotherapeutic treatment of CD44 overexpressing tumor cells." (PMID 24251041, 2013). "Within the numerous metastases, we found an overall homogeneous expression pattern of CD44 of approximately 100 % staining of all tumor cells." (PMID 23385555, 2013). "In MCF10DCIS xenograft tumors, CD44 knockdown decreased tumor size and weight as well as invasion markers." (PMID 23326564, 2013). "Studies have also found that CD44, a widely expressed endothelial cell surface HA receptor, affected the adhesion of tumor cells and lymphocytes." (PMID 23717428, 2013). "The highly differentiated C12 tumor type, and the C13 poorly differentiated tumor, demonstrate also a stable surface phenotype of CD44+/CD24+ and ALDH activity, which has been related to self-renewing CSC." (PMID 24358304, 2013). "CD44 is a surface glycoprotein that has been shown to bind to hyaluronan, as well as collagen, to promote tumor cell motility." (PMID 23521713, 2013). "Sorted CD44+CD24+ cells failed to establish large tumors within 3-4 weeks after challenge, whereas animals succumbed to the tumor within 4 weeks after challenge with sorted CD44+CD24- cells." (PMID 24324806, 2013). "Patients with HPVDNA+ tumors and an absent/weak CD44 intensity had a significantly better DFS (96% vs. 86%) and OS (95% vs. 80%) compared with patients with HPVDNA+ and medium/strong CD44 intensity tumor expression (P = 0.034 and P = 0.060, respectively)." (PMID 24156023, 2013). "When both markers were used the success rate of the c-Met+/CD44+combination yielded tumours in 80% of cases injected with 1000 cells compared to the success rate of ALDH1high cells, which yielded tumours in 66.6% of cases." (PMID 23533441, 2013). "Enrichment of CD44+ and CD44+CD133+ subpopulations of CSCs and enhanced expression of pluripotency factors further suggested the possibility of tumor recurrence or metastasis caused by SorR cells." (PMID 24244338, 2013). "Primary tumours with low overall CD44 VE expression level harbor metastatic clones with high expression level, which appears to be needed for entering the circulation and forming metastases." (PMID 23342032, 2013). "The expression of different CD44 isoforms has been correlated with the human tumor progression (rev." (PMID 23476138, 2013). "The use of chondroitin sulfate which binds CD44 overexpressed by tumor cells has recently been introduced." (PMID 23533772, 2013). "Similar in vitro and tumor growth in vivo results were obtained when ALDH+ cells were further selected for the stem cell markers CD44+ and CD24−." (PMID 24376586, 2013). "Unfortunately, not all HNSCC specimens were used in both transplantation phenotypes; however the specimens displayed an increase in tumour formation from 66.6% in the ALDH1high to 75% in the c-Met+/CD44+ cells." (PMID 23533441, 2013). "The non-metastatic adult primary tumour (AP) showed a higher expression level of all CD44 VEs than the metastatis newborn primary tumour." (PMID 23342032, 2013). "Findings to date had revealed that CD44+CD24low+ show greater sphere forming ability, more frequent tumour initiating cells (DT-22), and are driven by N1-ICD." (PMID 23982961, 2013). "We report here that the SBT-1214 alone, or in combination with CMC2.24, possesses significant activity against prostate CD133high/CD44+/high tumor-initiating cells." (PMID 24086245, 2013). "The CD44 VE expression level in HT168M1, which has a high base CD44 VE expression, varies within the metastases, ranging from barely detectable to approaching the level detected in circulating tumour cells." (PMID 23342032, 2013).